IL10 (interleukin 10)
Diseases named in the same sentence as IL10 in open-access papers (continued):
Sharing a sentence is not in itself a finding about the gene and the disease.
COVID-19 (continued). "The IL-10 level was within the reference range in 34 of 52 (65.4%) COVID-19 patients." (PMID 34123873, 2021). "It should be noted that the role of IL-10 in blocking the activity of IL-6 may be impaired in COVID-19 patients; however, further studies are needed to confirm this theory." (PMID 34251989, 2021). "Post-COVID-19 monocytes showed “back-to-normal” expression features such as the downregulation of IL-10 and the upregulation of CD4 and HLA-DRA, which was in agreement with the flow cytometry data showing an increase of HLA-DR expression in monocyte surface after recovery." (PMID 34572439, 2021). "Conversely, in COVID-19, the early induction of and sustained IL-10 levels might delay the onset of symptoms, possibly protecting the host against any potential initial immune-mediated complications." (PMID 34452323, 2021). "On the other hand, it is also possible that increased IL-10 may suppress antiviral adaptive immune responses and weaken resistance to bacterial superinfections in COVID-19 patients, as previously shown in animal models of influenza infection." (PMID 33232303, 2021). "Another novel and intriguing possibility that we have presented here is a potential “resistance” to IL-10’s classical anti-inflammatory actions, which may provide a mechanistic link between hyperglycemia/diabetes and severe COVID-19-related outcomes." (PMID 34234779, 2021). "To functionally test the role of cytokines on the viability of lymphocytes, we treated PBMCs isolated from healthy donors with selected groups of cytokines (e.g., IL-10, IL-15, IL-18, IL-8, IL-6, IL-1RA, IL-2RA, IL-4) for 36 h, using the maximum doses detected in COVID-19 serum." (PMID 34103487, 2021). "Furthermore, other cytokines were found to differentiate MIS-C and KD with shock or pediatric COVID-19, like IL-10 and TNFα." (PMID 34869111, 2021). "sST2, sTNFRSF1A, IL-10, and IL-15 may differentiate between survivors and patients who die from COVID-19 when measured throughout the entire hospitalization." (PMID 33232303, 2021). "In line with this, in an in vitro pilot study we showed that 5-FU may lower the burden of MDSC in severe COVID-19 patients, casing a lowered production of IL-10, IL-8, IL-17, and Th2 cytokines, while increasing the production of IFN-γ and IL-2." (PMID 33692788, 2021). "Moreover, specific cytokines such as IL-6, interleukin-8 (IL-8), and interleukin-10 (IL-10) are higher in patients with COVID-19-related ARDS." (PMID 34938289, 2021). "Interestingly, B cells from patients with acute COVID-19 displayed an IL-6/IL-10 cytokine imbalance in response to Toll-like receptor activation, skewed toward a pro-inflammatory phenotype." (PMID 33821250, 2021). "Take in account this idea, it would be expected that severe COVID-19 group showed imbalance between higher IL-6 levels and/or lower IL-10 levels, showing an impairment control of inflammation, which was associated with increased upper airway symptoms, as observed in our previous studies." (PMID 33717074, 2021). "High expression of IL-10 in COVID-19 patients could be one reason behind the delayed and weak adaptive response." (PMID 34305892, 2021). "A recent March paper has proposed a hypothesis that IL-10 up-regulation is responsible for COVID-19 uniqueness in comparison to other coronaviruses." (PMID 34454610, 2021). "This different and dynamic change in IL-6 and IL-10 levels, especially the decrease in the serum levels in the survivor group, has led to the clarification of the predictive role of cytokines on the prognosis of COVID-19 with prospective follow-up." (PMID 34855834, 2021). "Hence, it is possible that, in COVID-19 the induction of IL-10 solely serves to suppress adaptive immunity." (PMID 34251989, 2021).
COVID-19 (continued). "IL-10, which is known as a suppressor in the initiation phase of inflammation during COVID-19 and correlated strongly with proinflammatory IL-6 (r=0.5, p<0.0001) and TNF-α (r=0.6, p<0.0001), probably performing an immune-inhibitory mechanism as a negative feedback inflammation loop." (PMID 34858428, 2021). "A recent proteomic profiling study pointed to DC-SIGN as a mediator of genetic risk in COVID-19 and finally DC/L-SIGN expression is induced by proinflammatory cytokines such as IL-4, IL-6, IL-10 and IL-13, known to be overexpressed in severe SARS and COVID-19 cases." (PMID 34015061, 2021). "Furthermore, a cytokine analysis study of 131 plasma specimens demonstrated that plasma concentrations of several cytokines, including IFN-α, IFN-γ, IL-6, IL-8, and IL-10, were significantly increased in severe cases of COVID-19 compared to control groups." (PMID 34901061, 2021). "Notably, in COVID-19 patients the IL-10 levels were found significantly higher, at each time point, in patients who died compared to survivors." (PMID 33767713, 2021). "Also, a fatal outcome has been observed in patients with severe COVID-19 with kinetic variations in IL-6, IL-8, and IL-10, independently of sex, age, absolute lymphocyte count, direct bilirubin, hypertension, and chronic obstructive pulmonary disease." (PMID 34646263, 2021). "Severe COVID-19 cases also revealed higher levels of IL-2, IL-6, IL-10, and TNFα." (PMID 33869282, 2021). "To date, many studies have described an increased level of IL-10 in COVID-19 patients." (PMID 34575258, 2021). "Based on our results, we suggest that measuring levels of HGF, CXCL9, IL10-RB, MCP-3 and EN-RAGE could be further evaluated in larger cohorts as biomarkers of a “pre-morbid state” for the susceptibility to severe COVID-19." (PMID 34335580, 2021). "TNF-α, IFN-γ, IL-6, IL-8, IL-4, and IL-10 were dramatically elevated in COVID-19 patients." (PMID 34646834, 2021). "Cytokine storms with significant increases in IL-6 and IL-10 often occur in patients with severe COVID-19 and may play an important role in the development of lymphopenia, high neutrophils, and high mononuclear macrophages." (PMID 34712741, 2021). "Therefore, we advocate the inclusion of IL-10 into future cytokine profiling efforts in cells and tissues of COVID-19 patients including the respiratory tract and the CNS." (PMID 33746948, 2021). "Previous studies reported that COVID-19 is frequently associated with a massive production of 14 cytokines including IFN-γ, IL-1RA (IL1RN), IL-2RA, IL-6, IL-10, IL-18, HGF, MCP-3 (CCL7), MIG (CXCL9), M-CSF (CSF1), G-CSF (CSF3), MIG-1a (CCL3), CTACK (CCL27), and IP-10 (CXCL10)." (PMID 34262555, 2021). "Similarly, IL-4 and IL-10 were found to be increased in response to antigenic stimulation especially in the products of COVID-19 recovered individuals." (PMID 35003063, 2021). "Interestingly, recent studies have demonstrated that in the cytokine storm, a situation observed in severe COVID-19, the systemic levels of IL-6 and IL-10 are increased in the same way." (PMID 33717074, 2021). "In this study, the levels of TNF-α, IL-1α, IL-4, IL-6, IL-8, and IL-10, were measured through ELISA in sera from healthy volunteers as a control group, patients with moderate COVID-19, patients with severe COVID-19, and patients who had recovered from COVID-19." (PMID 33914789, 2021). "Here, we report an increased amount of IL-10 in COVID-19 vs. CAP patients." (PMID 35087533, 2021). "Similarly, miR-6741 was found to target many APOL1-related genes in COVID-19, increasing pro-inflammatory cytokines IL-6, IL-10, and IL-18, and CC chemokine ligand 5 (CXCL-5)." (PMID 35062245, 2021). "Serum levels of IL-7, IL-10 and IP-10 were elevated in COVID-19 asymptomatic cases compared to healthy controls, whereas IL-1RΑ, IL-1β, IL-6 and IP-10 were higher in symptomatic compared to asymptomatic COVID-19 patients." (PMID 34603318, 2021).
COVID-19 (continued). "ELISA assays revealed higher levels of EGFR and IL-10 in COVID-19 vs. CAP patients." (PMID 35087533, 2021). "This would suggest that the early induction of IL-10 in COVID-19 appears to be able to modify the course of the infection during the early stages of the disease, and certainly has implications for the therapeutic use of IL-10 in severe COVID-19 patients." (PMID 34452323, 2021). "Hence, the Th2 pathway is the predominant pathway during pregnancy; in addition, pregnant women have high levels of interleukin-10 (IL-10), which protects the mother from COVID-19." (PMID 34682679, 2021). "In particular, IL-10 was found increased more consistently than other cytokines in pediatric COVID-19 at hospital admission and earlier than most other cytokines in symptomatic adult patients, where its levels may show an association with disease severity." (PMID 33746948, 2021). "The higher IL-10 levels detected in our study in patients with COVID-19 who died may have reflected an extreme attempt to counteract severe lung inflammation." (PMID 33232303, 2021). "However, individuals with COVID-19 have higher levels of cytokines generated by Th2 cells (such as IL-4 and IL-10), which act as anti-inflammatory agents." (PMID 34945111, 2021). "The net effect of therapeutic IL-10 signaling blockade in COVID-19, whether increased vulnerability of the lung to inflammation or desirable antiviral immunity, is difficult to predict." (PMID 33746948, 2021). "A study in 71 patients hospitalized with COVID-19 found that levels of IL-6 and IL-10 were significantly higher in critically ill patients with severe COVID-19 compared to those with severe or mild form of disease, and patients with higher levels of IL-10 had shorter overall survival." (PMID 34945111, 2021). "The significance of the presence of IL10 in COVID-19 patients has been extensively described in the literature, this suggesting that IL-10 could discriminate disease progression." (PMID 33718270, 2021). "After adjusting the values for age, sex, baseline situation and COVID-19 severity, only IL-10 remained statistically significant (3.3 vs. 2.2 ng/dL, p = 0.042) with a trend towards signification in IL-23 (11.9 vs. 8.6 ng/dL, p = 0.082) and PIGF1 (1621.8 vs. 110.6 ng/dL, p = 0.071)." (PMID 34088273, 2021). "There were statistically significant increments of serum IL-6, IL-8 and IL-10 levels in patients with COVID-19, consistent with the hyperinflammatory syndrome that is so characteristic of severe and progressive disease, which rapidly dropped during convalescence." (PMID 33060840, 2021). "In contrast, Mo-MDSC were the dominant producers of IL-10 in severe COVID-19 patients." (PMID 33692788, 2021). "If IL-10 resistance is involved in COVID-19 adverse outcomes, then recent insights into the molecular aspects of anti-inflammatory IL-10 signaling may provide clues for novel therapeutic options." (PMID 34234779, 2021). "This clearly suggests the presence of IL-10 in COVID-19 severity." (PMID 34646263, 2021). "The reduction of IL-10 levels due to trimodulin treatment could therefore be beneficial for severe COVID-19 patients." (PMID 34177967, 2021). "Finally, we found that cytokine levels were acutely increased in severe and critical COVID-19 patients, particularly IL-6, IL-10, CRP and PCT." (PMID 33735325, 2021). "Interestingly, the systemic level of IL-10 was increased in COVID-19 patients in the second week following symptom onset." (PMID 34306612, 2021). "Another longitudinal analysis conducted in 71 COVID-19 patients revealed that a combination of IL-10, RANTES, and IL-1 receptor antagonist at first week of follow-up might be useful prediction biomarkers for patients’ outcome." (PMID 33410720, 2021). "Moreover, a significant correlation between COVID-19 severity and the serum concentrations of IL-1, IL-2, IL-6, IL-7, IL-10, TNF-α, G-CSF, CCL2, CCL3, CXCL8, and CXCL10 has been observed." (PMID 34209845, 2021).
COVID-19 (continued). "Additionally, a recent retrospective study collected data from 121 patients with COVID-19 and found increased levels of IL-6 (35.2%) and IL-10 (64.4%) on hospital admission." (PMID 34251989, 2021). "Here, we put forward the hypothesis that the early increase in IL-10 in COVID-19 contributes to more efficient viral spread compared to SARS." (PMID 33746948, 2021). "Furthermore, a significant increase in IL-10–producing regulatory T cells has been observed in the blood of patients with severe COVID-19, compared with those with moderate and mild disease and HVs." (PMID 33232303, 2021). "However, the striking observation between those who progressed to develop severe COVID-19 vs DHF was the IL-10 levels." (PMID 33199778, 2020). "However, compared with the survivors, IL-10 also increased significantly in our study, and the mortality of patients with severe COVID-19 complicated with diabetes was increased when IL-10 >10 U/mL." (PMID 33382747, 2020). "Also, that IL-6, IL-10 and interferon-gamma that are elevated in KD as well as in COVID-19, where these are shown to exert an inflammatory-mediated lung injury." (PMID 33162899, 2020). "In line with the herein results, patients with COVID-19 treated with MSCs showed lower levels of TNFα, whereas they showed lower levels of IL-6 and higher levels of IL-10 in plasma/serum samples." (PMID 33634100, 2020). "Furthermore, interleukin-10 (IL-10) has been reported to be a unique feature of the COVID-19 cytokine storm, and its concentrations strongly correlated with those of IL-6 and other inflammatory markers such as C-reactive protein." (PMID 33747973, 2020). "Similar to that in MERS-CoV infection, we found that IL-10 level was continuously elevated in critically ill patients and deceased cases with COVID-19, while IL-10 concentration transiently increased during hospitalization in severe cases and survivors and then fell to lowest level before discharge." (PMID 32854750, 2020). "This study raises the premise that the cytokine storm observed in COVID-19 cases might be correlated with disease severity, as IL-2, IL-7, IL-10, G-CSF, MCP-1, IP-10, TNF-α, and MIP-1α levels were higher in ICU patients compared with non-ICU ones." (PMID 33379162, 2020). "At 24h after the first clinical signs of COVID-19, interleukins (IL-1α, IL-1β, IL-6, IL-10), and IFNs (IFN-α2, IFN-β1, IFN-II) are significantly elevated, but the cellular sources of those cytokines are probably more epithelial and innate cells than T lymphocytes." (PMID 33335532, 2020). "The levels of IL-6 and IL-10 were higher in severe COVID-19 compared with those in active AOSD." (PMID 33552062, 2020). "COVID-19 ARDS patients had significantly higher plasma concentrations of CCL5 (p = 0.025) and non-significantly higher plasma concentrations of CXCL2 (p = 0.094), CXCL10 (p = 0.287), CD40 ligand (p = 0.125), IL-10 (p = 0.232), and GM-CSF (p = 0.332) compared with non-COVID-19 ARDS patients." (PMID 33138839, 2020). "Likewise, proteomic profiling approaches and targeted analysis of plasma proteins have shown high IL-6, IL-10, IL-8 and IFNγ levels in many COVID-19 patients." (PMID 33239683, 2020). "Moreover, a study evaluating a cohort of 44 hospitalized COVID-19 patients reported the existence of higher median fecal levels of IL-8 and lower levels of fecal IL-10 in COVID-19 patients compared with control individuals." (PMID 33379162, 2020). "Univariate analysis showed that the erythrocyte count, hemoglobin count, neutrophil count, lactate dehydrogenase, CK-MB, troponin I, procalcitonin, CRP, IL-6, and IL-10 may be factors that affect the severity of COVID-19." (PMID 33192519, 2020). "COVID-19 severity is often related to the exacerbation of the inflammatory process; in fact, high concentrations of cytokines [interleukin (IL)-2, IL-7, IL-10, GCSF, IP10, MCP1, MIP1A, TNFα] were observed in plasma of 13 patients admitted to the intensive care unit (ICU) of Wuhan in China." (PMID 33633566, 2020).
COVID-19 (continued). "Aside from direct virus-induced apoptosis, excessive release of cytokines observed in COVID-19 patients, e.g., IL-1β, IL-6, and IL-10, may lead to apoptosis in several cell types." (PMID 32854430, 2020). "Moreover, an increase in anti-inflammatory cytokine IL-10 in COVID-19 mothers is probably a regulatory mechanism crucial to regulate the inflammation and pregnancy maintenance." (PMID 32733490, 2020). "Studies have shown increased amounts of cytokines, such as IL-1β, IL-1ra, IL-6, TNF-α, IL-7, IL-8, IL-9, IL-10, FGF basic, G-CSF, GM-CSF, IFN-γ, IP-10, MCP-1, MIP-1a, MIP-1b, in the serum of COVID-19 patients, and the cytokine storm was associated with disease severity." (PMID 32426374, 2020). "The elevations of IL-6 and IL-10 are highly consistent in COVID-19." (PMID 32754163, 2020). "Collectively these data suggest that while IL-10 is likely to play a significant role in disease pathogenesis in both COVID-19 and dengue, the contribution to pathogenesis of severe dengue may be greater." (PMID 33199778, 2020). "They concluded that increased levels of Th17, as well as reduced number of Treg cells and associated determinants such as FoxP3, IL10 and TGF-β might perform a leading role in elevating inflammation and pathogenesis of COVID-19." (PMID 33244382, 2020). "However, also non-ICU patients (n = 28) showed increased plasma levels of IL-1β, IFN-c, IP-10, MCP-1, IL-4, and IL-10 even if the “cytokine storm” was higher in patients with a severe COVID-19." (PMID 33633566, 2020). "Cytokine storm was observed in severe COVID-19 patients with high levels of various serum cytokines, such as IL-2, IL-7, IL-10, TNF-α, granulocyte-colony stimulating factor (G-CSF), interferon gamma-induced protein 10 (IP-10; CXCL10), and monocyte chemotactic protein-1 (MCP-1)." (PMID 33251234, 2020). "COVID-19 patients have shown higher circulating levels of IL-10 than have healthy subjects." (PMID 33634100, 2020). "In support of this hypothesis, patients with more-severe COVID-19 had higher serum levels of IL-2R, IL-6, IL-10, and tumor necrosis factor alpha (TNF-α) than patients with milder disease." (PMID 32616514, 2020). "The levels of IL-6 and IL-10 were higher in severe COVID-19 compared with that in active AOSD." (PMID 33552062, 2020). "Even though inflammatory cytokine storms were thought to be a mechanism for COVID-19 progression, there was only an increase in IL-2, IL-4, IL-6, IL-10, TNF-α, and IFN-γ when comparing pneumonia patients with healthy people, but no significant increase in severe patients compared to mild patients." (PMID 32985562, 2020). "The IL-10 inhibitor in the treatment of COVID-19 also needs to be considered." (PMID 32754163, 2020). "Inflammatory cytokines such as TNF-α, interferon gamma (IFN-γ), interleukin 6 (IL-6), and IL-10 present in the plasma of COVID-19 patients induce mitochondrial reactive oxygen species production and impede mitochondrial oxidative phosphorylation and ATP production among other effects." (PMID 32854430, 2020). "Due to the elevated levels of IL-2R and IL-6 accompanied by the advancement of COVID-19, several cytokines secreted by T helper type 2 (Th2) cells that could neutralize the inflammatory responses including IL-4 and IL-10." (PMID 32822430, 2020). "Secondly, CD25+ hyperactivated T-cells may contribute to the elevation of some of the serum cytokines such as IL-10 in severe COVID-19 patients." (PMID 33178221, 2020). "Some authors have also reported a role for IL-6 and IL-10 in monitoring COVID-19 patients." (PMID 32397174, 2020). "Therefore, it is worth considering PBMT in COVID-19 as a useful tool in regulating IL-4 and IL-10 which correlate with Th-2 response." (PMID 32947974, 2020). "COVID-19 patients with diabetes had a poor prognosis, especially when they had two or more of the following abnormalities (χ2 = 58.62, P<0.001): lymphocyte count was ≤0.45×109/L, lactate dehydrogenase was >600 U/L, hsCRP was >90 mg/L and IL-10 was >10 U/mL." (PMID 33382747, 2020).